SULT2B1 (sulfotransferase family 2B member 1)
Diseases named in the same sentence as SULT2B1 in open-access papers (continued):
Sharing a sentence is not in itself a finding about the gene and the disease.
endometrial cancer (2 papers, 2010 to 2016). Primary or metastatic malignant neoplasm involving the endometrium (mucous membrane that lines the endometrial cavity). "As SULT2A1 is not expressed in either endometrial cancer or adjacent control endometrium, SULT2B1 is the major DHEA-specific SULT enzyme in endometrial cancer, and increased SULT2B1 expression has recently been reported in endometrial cancer, compared to adjacent control endometrium." (PMID 26924986, 2016).
hepatocellular carcinoma (2 papers, 2013 to 2022). A malignant tumor that arises from hepatocytes. "The relative SULT2B1 mRNA expression in human hepatocellular carcinoma cell lines showed a significant and direct correlation with the rate of cell proliferation (r = 0.931, R2 = 0.867)." (PMID 23593328, 2013). "In addition, the Human Protein Atlas also indicates that the expression of cholesterol hydroxylases is relatively limited to certain tumor types, such as hepatocellular carcinoma and melanoma, and is low in Sult2b1-expressing cancers." (PMID 35094065, 2022). "However, there are few reports describing the role of SULT2B1 in the progression of hepatocellular carcinoma." (PMID 23593328, 2013).
ichthyosis (2 papers, 2021 to 2025). Disorders of cornification that are characterized by visible scaling and/or hyperkeratosis of most or all of the skin. "They used a targeted NGS panel comprising 38 ichthyosis related genes and found pathogenic variants in the SULT2B1." (PMID 33807935, 2021). "Taken together, the present study of four Pakistani families supports previous research that biallelic mutations in TGM1, SULT2B1, SPINK5, and FLG cause human ichthyoses." (PMID 33807935, 2021).
cardiomyopathy (1 paper, 2025). A disease of the heart muscle or myocardium proper. "An association with an increased risk of cardiomyopathy has also been observed for the SULT2B1 gene, which contributes to the elimination of drugs such as anthracyclines and their toxic metabolites." (PMID 40413218, 2025). "Additionally, the variant SULT2B1-rs10426628 was associated with a 1.9-fold increased risk of cardiomyopathy in the combined cohort (95% CI: 1.2–2.5, p = 3.2 × 10−4)." (PMID 40413218, 2025).
cervical cancer (1 paper, 2024). A primary or metastatic malignant neoplasm involving the cervix. "Furthermore, inhibiting the expression of SULT2B1 with small molecules like verteporfin was reported to inhibit cervical cancer cell proliferation, migration, and invasion and promote cell apoptosis." (PMID 39280099, 2024).
colorectal cancer (1 paper, 2020). A primary or metastatic malignant neoplasm that affects the colon or rectum. "Also, they found that SULT2B1 played a crucial role in the oestrogen metabolic pathway and to be associated with colorectal cancer risk and survival." (PMID 32285560, 2020). "Li et al30 showed that SULT2B1 was significantly elevated in colorectal cancer tissues than in normal tissues." (PMID 32285560, 2020). "The genes in the reported colorectal cancer group include POLR1D, DGKB, SULT2B1 SMPD1 GOT2, MTHFD1L and ACADM." (PMID 32285560, 2020).
dermatitis (1 paper, 2025). An inflammatory process affecting the skin. "IMQ-induced dermatitis and neutrophil recruitment were exacerbated in the Sult2b1 knockout mice with a complete loss of CS." (PMID 41181147, 2025). "Furthermore, genetic deletion of Dock2 or intravenous administration of neutrophil-depleting antibodies alleviated IMQ-induced dermatitis in Sult2b1 knockout mice." (PMID 41181147, 2025). "To determine whether Sult2b1 expression and CS production are altered under psoriatic inflammatory conditions, we established an IMQ (toll-like receptor 7 agonist)-induced skin inflammation model." (PMID 41181147, 2025).
gastric tumor (1 paper, 2019). "In the current study, the roles of SULT2B1 and oxysterols on gastric epithelial function were investigated, and the incidence of carcinogenic agent-induced gastric tumor was compared between wild-type (WT) and SULT2B1 deletion (SULT2B1−/−) mice." (PMID 31757214, 2019). "SULT2B1 plays roles in normal gastric epithelial and gastric tumor cells." (PMID 31757214, 2019). "SULT2B1 mRNA expressions were higher in gastric tumors from patients with N3, but not N1 or N2 lymph node metastasis, than normal gastric tissue." (PMID 31757214, 2019).
infarction (1 paper, 2021). A localised pathological necrosis of tissue resulting from obstruction of the blood supply usually by a thrombus, an embolus, or vascular torsion. "We found that the after ischemia, Sult2b1 deficiency mice had enlarged infarction size and worsened neurological behaviors in association with augmented monocyte migration to inflamed brain and pro-inflammatory macrophage polarization." (PMID 34815805, 2021). "In conclusions, our present study demonstrated that Sult2b1-/- mice had a larger infarction and poorer behavioral performance due to the accumulation of pro-inflammatory macrophages in the damaged hemisphere." (PMID 34815805, 2021). "While neutrophil depletion did not dramatically change the infarction size, monocyte depletion alleviated the worse stroke outcome in Sult2b1-/- mice." (PMID 34815805, 2021).
Insulin resistance (1 paper, 2025). Increased resistance towards insulin, that is, diminished effectiveness of insulin in reducing blood glucose levels. "Here, by using the high-fat diet (HFD)-induced obesity model and the genetic obese ob/ob mice, we showed that genetic ablation of Sult2b1 protected mice from developing obesity and related insulin resistance, hepatic steatosis, and adipose tissue inflammation." (PMID 40456448, 2025). "More tissue-specific investigations in the future, including the creation and use of tissue-specific Sult2b1 knockout mice, are necessary to pinpoint the tissues or cell types that are responsible for the role of Sult2b1 in the development of obesity and insulin resistance." (PMID 40456448, 2025). "Our results suggested that inhibition of SULT2B1 may be explored for managing obesity and insulin resistance by increasing energy expenditure and inhibiting intestinal fat absorption." (PMID 40456448, 2025).
ischemia (1 paper, 2021). A hypoperfusion of the BLOOD through an organ or tissue caused by a PATHOLOGIC CONSTRICTION or obstruction of its BLOOD VESSELS, or an absence of BLOOD CIRCULATION. "For Sult2b1, the expression in the ischemic hemisphere was significantly increased from 4 h after ischemia, while the Sts had decreased compared to the sham control groups." (PMID 34815805, 2021).
ischemic stroke (1 paper, 2021). A stroke disorder caused by obstruction of blood flow to the brain, due to thrombotic (local blood clot formation) or embolic (due to a blood clot or other material traveling from another site) event. "This study aimed to investigate the function of Sult2b1 and cholesterol sulfate in the neuroinflammation after ischemic stroke." (PMID 34815805, 2021). "In present study, we investigated the significance and potential mechanisms of Sult2b1 in ischemic stroke." (PMID 34815805, 2021). "Furthermore, Sult2b1-/- mice had a lower survival rate than WT mice in 30 days after ischemic stroke." (PMID 34815805, 2021).
kidney cancer (1 paper, 2019). Primary or metastatic malignant neoplasm involving the kidney. "SULT2B1 showed substantial higher expression in kidney cancer as compared to normal tissue, which was corroborated by IHC staining." (PMID 31655797, 2019).
liver cancer (1 paper, 2024). An epithelial or non-epithelial malignant neoplasm that arises from the liver. "An increased expression of SULT2B1 in colorectal, breast, endometrial, and liver cancers has been reported to promote tumor growth and poor prognosis." (PMID 39280099, 2024).
lung carcinoma (1 paper, 2019). "Glutathione S-Transferase Omega 1 (GSTO1), Sulfotransferase Family 2B Member 1 (SULT2B1), ADH1A, ADH1B, and ADH1C were downregulated in lung cancer versus normal tissue, while ALDH3A2 and MTHFD2 were upregulated in lung cancer tissue versus normal adjacent tissue." (PMID 31717324, 2019).
malaria (1 paper, 2019). Malaria is a serious and sometimes fatal disease caused by a parasite that commonly infects a certain type of mosquito which feeds on humans. "More work will be needed to determine if Lxrα is activated or inactivated in this model of malaria and if this is related to Sult2b1 upregulation and enhanced sulfation of oxysterols." (PMID 31299982, 2019).
metabolic syndrome (1 paper, 2025). A cluster of metabolic risk factors for CARDIOVASCULAR DISEASES and TYPE 2 DIABETES MELLITUS. "We have previously reported that hepatic overexpression of Sult2b1 in transgenic mice or treatment with Sult2b1-derived metabolite cholesterol sulfate protected mice from obesity and associated metabolic syndrome." (PMID 40456448, 2025). "Our results suggest that targeting SULT2B1 may represent a novel strategy to combat obesity and related metabolic syndrome." (PMID 40456448, 2025).
Obesity (1 paper, 2025). Accumulation of substantial excess body fat. "In an independent model of obesity, we bred the Sult2b1KO allele into the genetically obese ob/ob mice to create ob/ob mice deficient in Sult2b1, termed obsk mice." (PMID 40456448, 2025). "To our surprise, we found the loss-of-function Sult2b1 knockout (Sult2b1KO) mice were also protected from obesity." (PMID 40456448, 2025). "Taken together, our results demonstrated that the ablation of Sult2b1 inhibits intestinal lipid absorption potentially by interfering with lipoprotein assembly, which leads to the decrease of systemic fatty acid level and ameliorates obesity." (PMID 40456448, 2025). "Our results suggest that inhibiting SULT2B1 may be a promising approach to combat obesity and its comorbidities." (PMID 40456448, 2025). "SULT2B1 was previously known to decrease serum and hepatic lipid levels by deactivating the oxysteroid-derivative endogenous LXR agonists, and inhibit gluconeogenesis by targeting HNF4α, both of which may have contributed to the alleviation of metabolic abnormalities in obesity." (PMID 40456448, 2025).
prostate adenocarcinoma (1 paper, 2022). "Cholesterol sulfate was produced by hydroxysteroid sulfotransferase 2B1 (SULT2B1) and accumulates in human prostate adenocarcinoma and precancerous prostatic intraepithelial neoplasia (PIN) lesions, which indicates the functional roles of cholesterol sulfate in these diseases." (PMID 36360204, 2022).
steatosis (1 paper, 2014). Increased lipid within the cytoplasm of cells. "Based on our transcriptomic results, this phenomenon can be directly related to the under-transcription of sulfotransferase 2B1 (SULT2B1) at 6 hours post-BaP-exposure, an enzyme known to protect the liver from steatosis and to inhibit lipogenesis." (PMID 25103525, 2014).
Stroke (1 paper, 2021). Sudden impairment of blood flow to a part of the brain due to occlusion or rupture of an artery to the brain. "Combined with CyTOF and immunofluorescence techniques, we demonstrated that after stroke, the peripheral monocyte-derived macrophages were the dominant cell type promoting the pro-inflammatory status in Sult2b1-/-mice." (PMID 34815805, 2021). "To further confirm these results, we performed the IF staining, which showed that stroke resulted in a significant increase in CD68+ and iNOS+ cells in Sult2b1-/- mice." (PMID 34815805, 2021).
ulcerative colitis (1 paper, 2022). An inflammatory bowel disease involving the mucosal surface of the large intestine and rectum. "The levels of cholesterol and cholesterol sulfate, as well as the expression of Sult2b1 and genes involved in cholesterol biosynthesis, are significantly higher in inflamed tissues from patients with ulcerative colitis than in intestinal mucosa from healthy controls." (PMID 35908039, 2022).
ulcers (1 paper, 2023). "Furthermore, Sult2b1−/− mice exhibited markedly increased counts and areas of SI ulcers, compared with those in Sult2b1+/+ mice, and these ulcerative lesions were dramatically ameliorated by CS administration." (PMID 37006281, 2023).
tumor (11 papers, 2013 to 2025). "Herein, through the utilisation of single‐cell sequencing and proteomics, we identified sulfotransferase SULT2B1 as a novel metastatic tumour marker of CC, which was associated with poor prognosis." (PMID 38372484, 2024). "Cholesterol sulfate, synthesized by sulfotransferase 2B1 (SULT2B1) in tumor cells, is secreted to suppress dedicator of cytokinesis protein 2 (DOCK2) enzymatic activity in T cells, leading to CD8+ T cell exhaustion." (PMID 40270603, 2025). "The expression of SULT2B1 exhibited a significant correlation with tumour stage and prognostic in CC." (PMID 38372484, 2024). "Despite the sc‐RNA sequencing data retrieved from the GEO database lacking corresponding information on adjacent cancerous tissues, our analysis revealed a notably elevated expression of SULT2B1 within metastatic CC tumour tissues." (PMID 38372484, 2024). "And we also found that SULT2B1 expression was significantly higher in tumour tissues of digestive tract cancers in the TCGA database." (PMID 38372484, 2024). "Results showed that SULT2B1‐KO significantly inhibited tumour proliferation, induced apoptosis of tumour cells and repressed lipid metabolism activities of tumours in situ, along with decreased SCD1 expression." (PMID 38372484, 2024). "Functional analysis proves that SULT2B1 overexpression in vitro reduces tumor cell proliferation and retard tumor growth in vivo, while SULT2B1b knockdown promotes ESCC progression." (PMID 39280099, 2024). "Herein, we identified SULT2B1 as a novel metastasizing tumour marker for CC, which promoted lipid metabolism and metastasis capacity of CC cells by directly interacting with stearoyl‐CoA desaturase (SCD1)." (PMID 38372484, 2024). "In vivo experiments demonstrated that the overexpression of SULT2B1 facilitated tumour proliferation, increased SCD1 expression, facilitated lipid metabolism activities and promoted distant metastasis." (PMID 38372484, 2024). "The study suggested that reduced expression of SULT2B1 upregulates Per1 gene expression, a circadian clock gene that is involved in tumor initiation and malignant progression." (PMID 39280099, 2024). "Overexpression of SULT2B1 promotes cancer cell proliferation by reducing tumor infiltration with lymphocytes as well as reducing the expression level of macrophages, neutrophils, B cells, CD4+ cells, CD8+ cells, and dendritic cells." (PMID 39280099, 2024). "In tumor xenografts of SULT2B1-RNAi-LV cells, cyclinB1, MYC and BCL2 protein levels decreased, while no significantly differences in cyclinD1 protein levels was observed between the two groups." (PMID 23593328, 2013). "As qPCR results indicated that, SULT2B1 mRNA levels in the human hepatocarcinoma tumor tissues showed much higher levels than those of the para-tumor tissues in the clinical samples." (PMID 23593328, 2013). "Recent research has suggested that high expression of SULT2B1 could potentially accelerate the progression of liver cancer by impacting the tumour microenvironment." (PMID 38372484, 2024). "Importantly, in humans, the expression of cholesterol hydroxylases is relatively limited to certain tumor types and is low in Sult2b1-expressing cancers." (PMID 35094065, 2022). "Our data suggested that SULT2B1 expressed higher in the human hepatocarcinoma tumor tissues compared to those para-tumor tissues, which suggested that SULT2B1 may play an important role in the hepatocarcinoma cell growth." (PMID 23593328, 2013). "Knock-down of SULT2B1 significantly suppressed tumor growth in vivo as compared with NC-GFP-LV." (PMID 23593328, 2013). "Therefore, we speculated that SULT2B1 might promote tumour cell lipid metabolism and metastasis by regulating a key enzyme in lipo‐metabolism pathway." (PMID 38372484, 2024).
tumor (continued). "Moreover, it provided a solid experimental basis for future clinical applications of targeted drugs that inhibited tumour cell lipid metabolism to suppress distant metastasis, as well as the potential use of lovastatin to reduce distant metastasis in CC patients with high expression of SULT2B1." (PMID 38372484, 2024). "We also found that genetic deletion of Sult2b1 in Pan02 (Pan02-ΔSULT) suppressed tumor growth in C57BL/6 mice, with an increased percentage of tumor-infiltrating CD8+ T cells." (PMID 35094065, 2022). "Tumor growth rate and weight, and Ki67 expression were reduced in nude mice by sh-OLR1 treatment, which was negated by further oe-SULT2B1 treatment." (PMID 34921134, 2021). "Our results showed that SULT2B1 expression in tumour tissues was higher than that in patients without distant metastasis or normal tissues." (PMID 38372484, 2024). "As indicated by western blot analysis, expression of LOX-1, c-MYC, and SULT2B1 in tumor tissues of nude mice was lowered by knocking down OLR1, whilst SULT2B1 expression in tumor tissues of nude mice was markedly strengthened by oe-SULT2B1 treatment in the presence of sh-OLR1As." (PMID 34921134, 2021). "Despite this, the reason for the high expression of SULT2B1 in tumours has not been established." (PMID 38372484, 2024).
cancer (7 papers, 2022 to 2025). A tumor composed of atypical neoplastic, often pleomorphic cells that invade other tissues. "Genetic variation of the SULT2B1 is reported to be associated with various pathological conditions, including autosomal recessive ichthyosis, cardiovascular disease, and different types of cancers." (PMID 39280099, 2024). "For instance, numerous studies reported the association of genetic variation or change in the expression of SULT2B1 in various diseases and cancer types." (PMID 39280099, 2024). "On the other hand, SULT2B1 knockdown inhibits cancer cell proliferation and reduces invasion and migration." (PMID 39280099, 2024). "Given the critical role of abnormal metabolism in cancer progression, and the involvement of SULT2B1 in lipid metabolism, we hypothesised that SULT2B1 may promote metastasis in CC through its participation in lipid metabolism." (PMID 38372484, 2024). "The inhibition of SULT2B1 hindered cell growth and cell cycle arrests, especially in cancer cells." (PMID 36197921, 2022). "Several DEGs identified were known to be involved in several cancers, these include the microRNA MIR-186 and the PPP1R1C genes, both of which were up-regulated in our study, and NGEF, C9orf163, INKA2-AS1 and SULT2B1 which were found to be downregulated." (PMID 36197921, 2022). "Overall considering the antioxidant stress and anti-aging functions of BHB target proteins including SOD, GATA3 and SULT2B1, the differences in BHB content may imply cancer cells with various ability to resist surrounding stress." (PMID 38782922, 2024). "In addition, SULT2B1 and MALAT1 have been extensively studied in the field of cancer in recent years." (PMID 39525632, 2024).
infection (2 papers, 2019 to 2022). The state of being infected such as from the introduction of a foreign agent such as serum, vaccine, antigenic substance or organism. "We used adenovirus (Ad)-SLC10A6 infection to overexpress SLC10A6 in SULT2B1-KO HT-29 cells, which was confirmed using immunofluorescent staining and western blotting." (PMID 35908039, 2022). "Sult2b1, which was greatly upregulated at days 6 and 12 of infection, sulfates oxysterols and its increased expression is associated with reduced cellular sterol levels and reduced activity of Lxr target genes in different contexts." (PMID 31299982, 2019).
cardiovascular disease (1 paper, 2024). "In fact, SULT2B1 genetic variation has been proven to be involved in various disease conditions like autosomal recessive ichthyosis, cardiovascular disease, and various malignancies." (PMID 39280099, 2024).